CASP8 (caspase 8)
Diseases named in the same sentence as CASP8 in open-access papers (continued):
Sharing a sentence is not in itself a finding about the gene and the disease.
glioma (continued). "Findings indicate that free of Bax from Mcl-1-mediated sequestration, promotion of Bax conformational change favoring mitochondrial translocation and oligomerization, and relief of caspase 8 inhibition are targets for indomethacin-induced glioma apoptosis." (PMID 31952288, 2020). "Overexpression of miR-106b-5p in glioma cells can promote significant cell proliferation and mediate apoptosis of glioma cells by targeting CASP8." (PMID 32511270, 2020). "In a rat glioma model, apoptosis was induced by activation of CASP8 and inhibition of RIPK1/RIPK3 complex." (PMID 29912993, 2018). "After cilengitide treatment of glioma cells, apoptosis-related genes (i.e., caspase 8, desmoplakin, and protein kinase C, zeta) were upregulated." (PMID 23667810, 2013). "The importance of CASP8 in TRAIL resistance in gliomas has been reported as well, while the data of other studies have strongly suggested TRAIL sensitivity to be CASP8-independent and DR4-specific." (PMID 22672670, 2012). "When comparing the relative expression of Caspase-8 protein in normal and cancer tissues, Caspase-8 levels have been reported to be aberrantly low in kidney, prostate, colorectal and breast tumors, and conversely, unexpectedly high in glioma, cervix, pancreas and liver cancer." (PMID 37444381, 2023). "In vitro, CASP8 silencing inhibited the migration and invasion of glioma cells." (PMID 35296768, 2022). "Furthermore, it has been reported that methylation of the Caspase-8 (CASP8) gene promoter in glioma cells is governed by both DNMT1 and DNMT3A, indicating a potential collaboration and concerted action of DNMTs." (PMID 36555712, 2022). "The pyroptosis-related gene CASP8 is a molecular switch controlling tumor cell pyroptosis and it could promote the progression of glioma." (PMID 36120583, 2022). "Furthermore, RES is able to induce apoptosis by both the caspase-8-dependent and caspase-9-dependent pathways in U251, U87, and C6 glioma cells." (PMID 35328780, 2022). "Finally, we analyzed the core intersection gene CASP8 from the perspectives of immune checkpoints, immune cell infiltration, prognosis, and protein expression, which unveiled that CASP8 can be used as a novel potential glioma prognosis biomarker." (PMID 36466844, 2022). "We found CASP8 was significantly overexpressed in a variety of cancers, including glioma." (PMID 36466844, 2022). "Similarly, a positive correlation between CASP8 and increased glioma histopathological grades was observed." (PMID 36466844, 2022). "Furthermore, the result indicated that the OS of glioma patient groups with high CASP8 expression was evidently shortened, and positively correlated with multiple inhibitory immune checkpoints." (PMID 36466844, 2022). "In vitro, we found that CASP8 promotes the progression of glioma cells." (PMID 35069683, 2021). "However, our data indicated that higher CASP8 expression is found in glioma than control, the expression is highest in WHO IV, WHO III takes second place, and WHO II is the lowest, and the elevated CASP8 is associated with poor overall survival." (PMID 35069683, 2021). "Previous research stated that p62 might be involved in the neurodegenerative processes because the overexpression of p62 promoted apoptosis through increasing production of caspase-8, and the knockdown of p62 reduced human glioma cell death." (PMID 32714192, 2020). "Our study found that emodin could induce apoptosis by activating caspase-3; however, surprisingly, the protein levels of caspase-8 were decreased in glioma U251 cells treated with emodin." (PMID 30924024, 2020).
glioma (continued). "In summary, our study has revealed that low PIP-TMZ treatment inhibits the proliferation of glioma cells by reducing cell viability, inducing apoptosis and activation of caspase-8/-9/-3, activation of JNK/p38 MAPKs, inhibiting wound healing, and MMP depolarization." (PMID 32693671, 2020). "Importantly, the bioinformatics analysis of microarray gene expression data derived from a set of high-grade human gliomas, shows that high Caspase-8 expression levels correlate with a worse prognosis." (PMID 28594322, 2017). "Finally, the expression of neuro CASP8 expression was higher in glioma compared to controls." (PMID 38304870, 2024). "In addition, the highly expressed CASP8 in gliomas may be a feedback regulatory mechanism evolved by glioma to avoid necroptosis." (PMID 36466844, 2022). "Furthermore, silencing CASP8 inhibited the migration and invasion of glioma cells." (PMID 35296768, 2022). "However, our results showed that CASP8 was highly expressed in glioma." (PMID 36466844, 2022). "We found that the human H4 glioma cell-killing effects of aspirin involved mitochondria-mediated apoptosis accompanied by endoplasmic reticulum (ER) stress, Noxa upregulation, Mcl-1 downregulation, Bax mitochondrial distribution and oligomerization, and caspase 3/caspase 8/caspase 9 activation." (PMID 32545774, 2020). "Shikoinin could increase caspase 3, caspase 8 and caspase 9 activities in glioma cells." (PMID 24714453, 2014). "Due to the profound impact on survival in glioma patients, 4 genes, namely IFNGR2, GLUD1, PPIA, and CASP8 were identified." (PMID 36466844, 2022). "Caspase-8 can also stimulate the NF-kB pathway and upregulate the secretion of IL-8, IL-1β, IL-6, VEGF and MCP-1, improving temozolomide resistance in gliomas." (PMID 36605437, 2022). "Downregulation of cathepsin B can induce caspase-8-mediated apoptosis and initiates a partial extrinsic apoptotic cascade in SNB19 human glioma cells." (PMID 31752209, 2019). "The possible participation of caspase 8, Bid and Bax in the antineoplastic effect induced by Cas III-ia on C6 glioma cells was examined by Western blot analysis." (PMID 22540380, 2012). "LM-G-4, a TRAIL resistant line, expressed higher levels of DR5, caspase-8 and FADD than D2247, arguing that factors other than the levels of these proteins influence TRAIL sensitivity in glioma cells." (PMID 18594532, 2008). "Next, the expression analysis of CASP8 in human astrocyte NHA and 5 immortalized human glioma cell lines (LN-229, U87-MG, A172, U118-MG, and U251-MG) showed that CASP8 expression in astrocytes was lower than that in 5 human glioma cell lines." (PMID 36466844, 2022). "On probing the initiator caspases, both caspase 8 (extrinsic or ligand mediated pathway) and caspase 9 (intrinsic or mitochondrial pathway), we observed that neither of these caspases were activated upon AEBP1 down regulation in U138MG glioma cells." (PMID 31601918, 2019). "The increase in caspase 8 levels observed in peptide-TTs is in agreement with the finding that caspase 8 is absent or at low levels in many resected glioma samples." (PMID 28412744, 2017). "As inhibition of USP9X resulted in caspase 3 and caspase 8 activation and increased the rates of apoptosis, USP9X might promote cell survival by inhibiting apoptosis in glioma cells." (PMID 27783990, 2016). "The results indicated that glioma cells with the knockout of caspase-8 were more sensitive to bufalin than those without caspase-8, and bufalin may be a potential drug for glioma therapy." (PMID 36313284, 2022). "Knockdown of FADD expression decreased TMZ induced PARP1 cleavage, activation of CASP8 and CASP3, and degradation of BCL2 and BCL-XL in ATRX knockout cells, indicating that suppression of FADD is responsible for ATRX mediated PARP1 stabilization and TMZ resistance in glioma cells." (PMID 32194873, 2020).
glioma (continued). "This implies that many patients with glioma may not benefit from death ligand-based treatments, unless caspase-8 protein expression can be elevated, such as by VDAC1-based peptides, as demonstrated here." (PMID 28412744, 2017). "In addition, the previous researches had also shown cytokine neuregulin 1 (Nrg1) could upregulate the L1CAM expression to enhancing the migration of glioma cells, and TGF-β1 could mediate L1CAM expression, then led to the downregulation of caspase-8 and apoptosis resistance." (PMID 32509846, 2020). "Of the 11 pyroptosis regulators, 8 revealed remarkable distinctions between glioma and normal tissues, while CASP5, CASP8, and GSDMC did not." (PMID 35620284, 2022). "Aside from the possible role in immune surveillance, some of the glioma cells are resistant to Fas-induced apoptosis, possibly due to low levels of Fas expression, or absence of FADD or caspase 8 expression." (PMID 20942909, 2010). "Additionally, DNA methylation analysis demonstrated that the promoter methylation levels of AIM2, CASP1, CASP8, NLRP3, and ZBP1 are significantly lower in gliomas than in non-tumor brain tissues." (PMID 39901195, 2025). "Recent studies in medulloblastoma and glioma found similar responses; however, in the case of glioma, the non-stem cell population displayed moderate sensitivity to TRAIL, as opposed to the stem cells which were resistant partly due to a lack of caspase-8." (PMID 27330806, 2016). "However, this induction of apoptotic features did not fully explain the cell death induced by 2OHOA in 1321N1, SF-767 and U118 glioma cells as we did not observed PARP degradation induction in SF-767 and U118 cells treated with 2OHOA, as well as Caspase 8 proteolysis in SF-767 cells." (PMID 23133576, 2012).
glioblastoma (50 papers, 2003 to 2025). The most malignant astrocytic tumor (WHO grade IV). "In the present study, treatment of human TMZ-sensitive glioblastoma cells with enzalutamide caused much greater activation of caspase-9 than caspase-8." (PMID 36235203, 2022). "In another study performed on 76 patients associated with glioblastomas, the loss of caspase-8 by methylation of its promoter reached more than 50% of the patients." (PMID 31248188, 2019). "Being p62 a key adaptor protein in autophagy machinery, we asked whether Caspase-8 expression may affect autophagic flux causing p62 accumulation in glioblastoma." (PMID 41053176, 2025). "CASP8 mutations are associated with increased risks of cancer, and low expression of CASP8 is closely associated with poor prognosis in patients with cancer; however, CASP8 expression was significantly upregulated in glioblastoma multiforme (GBM) and pancreatic adenocarcinoma (PAAD)." (PMID 35246158, 2022). "However, recent studies reported that Caspase-8 expression was retained, and high-level expression of Caspase-8 may be associated with a worsening prognosis in glioblastomas." (PMID 37153540, 2023). "Mechanistically, we demonstrate that Src-dependent phosphorylation of Caspase-8 on Tyrosine 380 (Y380), frequently reported in cancers including glioblastoma, sustains mTORC1 activation, thus promoting energy metabolism." (PMID 41053176, 2025). "Conversely, IL-1RA and Tolcapone at 1 μg/mL and 20 μM/mL, respectively, increased the expression of Caspase-8 and Caspase 3 for induction of apoptosis and cell death of glioblastoma U87 cells." (PMID 40725140, 2025). "By performing transcriptomic, proteomic and phosphoproteomic analyses on glioblastoma cellular models, we identify Caspase-8 as an unexpected modulator of NRF2." (PMID 41053176, 2025). "Src-induced phosphorylation of caspase-8 on Y380 was also found to drive the assembly of a soluble complex, containing IKKα, IKKβ and p65, that tiggers NF-kB activation in glioblastoma cells, leading to inflammation and angiogenesis." (PMID 38534365, 2024). "Of note, regarding glioblastoma, high levels of Caspase-8 expression have been proposed to be part of the molecular signature that identified the mesenchymal subtype." (PMID 37444381, 2023). "In glioblastoma, caspase-8 promotes the expression of various cytokines, angiogenesis, and tumorigenesis." (PMID 36861130, 2023). "Conversely, tumors such as glioblastoma, pancreatic cancer, head and neck cancer display unchanged or upregulated levels of Caspase-8." (PMID 37444381, 2023). "More interestingly, the correlation between the levels of Caspase-8 expression and glioblastoma patients’ survival has also been investigated." (PMID 37444381, 2023). "It is known that haloperidol was able to induce apoptosis and increase caspase-8 expression in other glioblastoma cell lines." (PMID 36447028, 2022). "In contrast, caspase-8 expression increases in glioblastoma, promoting sustained NFκB activation and the transcription of several cytokines." (PMID 33026575, 2021). "The levels of IL-8, IL-6, IL1β, CCL2, and VEGF correlate with caspase-8 expression levels, thereby painting caspase-8 as a modulator of angiogenesis and inflammation in glioblastoma." (PMID 33026575, 2021). "Regarding the death receptor-mediated pathways, gene expression of several members of the TNF receptor family as well as FAS and FADD but also caspase-8 and caspase-7 was found to be reduced in human glioblastoma tissue." (PMID 34485282, 2021). "Pinoresinol facilitated DISC formation to trigger a caspase-8-dependent apoptotic cascade activation in TRAIL-resistant glioblastoma cells." (PMID 31534206, 2019). "Analyses of apoptotic signaling events revealed that pinoresinol enhanced the formation of TRAIL-mediated death-inducing signaling complex (DISC) and complete processing of procaspase-8 within the DISC in glioblastoma cells, in which caspase-8 was inactivated." (PMID 31534206, 2019).
glioblastoma (continued). "In glioblastomas, like CASP8, more than 40% of the cell lines studied displayed significant methylation in DR4 gene promoter, explaining at least partially the heterogeneity of the disease." (PMID 31248188, 2019). "Another level of regulation includes the control of caspases, as L1CAM suppresses transcription of caspase-8 in glioblastoma." (PMID 31455004, 2019). "Pretreatment with caspase inhibitors diminishes the activities of caspase 8, 9, and 3 and maintains the percentage of viable glioblastoma cells, indicating that α-H induced cell apoptosis through both the extrinsic and the intrinsic pathways." (PMID 31551765, 2019). "As already pointed out, the expression of Caspase-8 is very heterogeneous in different glioblastoma cell lines as well as in different glioblastoma primary tumors." (PMID 30501030, 2018). "TRAIL induces apoptosis even when Bcl-2 is overexpressed in the tumor, since the former activates caspase-8, Bid, and caspase-9 in glioblastoma LN-229 cells when cultured with TRAIL." (PMID 30486451, 2018). "Several studies provided evidence for very heterogeneous levels of Caspase-8 expression in glioblastoma cell lines as well as in primary tumors." (PMID 30501030, 2018). "Intriguingly, in glioblastoma models, Caspase-8 can promote NF-κB-dependent expression of several cytokines, angiogenesis, and in vitro and in vivo tumorigenesis." (PMID 30501030, 2018). "We have recently shown that in glioblastoma cells lines Caspase-8 can sustain neoplastic transformation in vitro and tumor growth in vivo." (PMID 30501030, 2018). "Further experiments showed that, when grown in the laboratory, glioblastoma cells with less Caspase-8 were more sensitive to a chemotherapeutic drug called temozolomide." (PMID 28594322, 2017). "As such, these findings reveal a clear link between Caspase-8 and the formation of new blood vessels by glioblastomas." (PMID 28594322, 2017). "To further confirm the relevance of DR5 upregulation after Notch1 knockdown for TRAIL-induced apoptosis in glioblastomas, we analyzed the extent of caspase-8 activation and DISC-formation following TRAIL-treatment." (PMID 26469969, 2015). "The current study reveals new and important information on MGMT, GATA6 and CASP8 promoter methylation in glioblastoma." (PMID 22672670, 2012). "Cox regression analysis showed patient age, treatment, MGMT, GATA6 and CASP8 as independent predictors for glioblastoma patient outcome (p < 0.05)." (PMID 22672670, 2012). "The tendency of association between methylation of CASP8 and DR4 in glioblastomas was noted: co-methylation was observed in 28.4% (21/74) of tumors." (PMID 22672670, 2012). "The methylation status of MGMT, CD81, GATA6, DR4, and CASP8 in 76 patients with primary glioblastomas was investigated." (PMID 22672670, 2012). "Hypermethylation of CASP8 has been showed as a frequent feature of relapsed glioblastoma compared with the corresponding primary tumors." (PMID 20132554, 2010). "Basal caspase 3 and caspase 8 activity promotes migration and invasiveness in glioblastoma cells and inhibition of caspases decreases the migration and the invasiveness of cells." (PMID 19675677, 2009). "More recently, we and others showed that the aberrant activation of Src and the subsequent phosphorylation of Caspase-8 on Y380 drive also the acquisition by glioblastoma cells of new non canonical functions of Caspase-8 that overall, sustain tumorigenic progression and a poor prognosis." (PMID 41053176, 2025). "In addition, IL-1RA and Tolcapone induced apoptosis via increasing the levels of apoptotic markers like Caspase-8 and Caspase-3, suggesting that both IL-1RA and Tolcapone are promising drugs against glioblastoma." (PMID 40725140, 2025). "Indeed, de novo Caspase-8 expression has been reported in glioblastoma (GBM), compared to normal tissue, and its overexpression has been demonstrated to drive tumor aggressiveness and resistance to therapy in different ways." (PMID 41053176, 2025).